POPDC1 (popeye domain cAMP effector 1)
Description:
Cell adhesion molecule involved in the establishment and/or maintenance of cell integrity. Involved in the formation and regulation of the tight junction (TJ) paracellular permeability barrier in epithelial cells. Plays a role in VAMP3-mediated vesicular transport and recycling of different receptor molecules through its interaction with VAMP3. Plays a role in the regulation of cell shape and movement by modulating the Rho-family GTPase activity through its interaction with ARHGEF25/GEFT. Induces primordial adhesive contact and aggregation of epithelial cells in a Ca(2+)-independent manner. Also involved in striated muscle regeneration and repair and in the regulation of cell spreading (By similarity). Important for the maintenance of cardiac function. Plays a regulatory function in heart rate dynamics mediated, at least in part, through cAMP-binding and, probably, by increasing cell surface expression of the potassium channel KCNK2 and enhancing current density. Is also a caveolae-associated protein important for the preservation of caveolae structural and functional integrity as well as for heart protection against ischemia injury.
Synonyms: BVES; POP1; HBVES; CARICK; LGMD2X; LGMDR25
Tractability: Antibody: UniProt places it where antibodies can reach, with high confidence; its Gene Ontology location is reachable by antibodies, with high confidence; UniProt predicts a signal peptide or a membrane-spanning region; the Human Protein Atlas places it where antibodies can reach.
Gene: Protein-coding gene on chromosome 6 (105,096,822 to 105,137,216, reverse strand). Ensembl gene ENSG00000112276.
Subcellular location: Lateral cell membrane; Cell junction, tight junction; Membrane; Cell membrane, sarcolemma; Membrane, caveola
Subcellular location (Human Protein Atlas): Cell Junctions; Plasma membrane
Gene Ontology:
Molecular function: protein binding; structural molecule activity; cAMP binding
Biological process: epithelial cell-cell adhesion; heart development; skeletal muscle tissue development; muscle organ development; positive regulation of locomotion; positive regulation of receptor recycling; regulation of cell shape; regulation of GTPase activity; regulation of membrane potential; response to ischemia; striated muscle cell differentiation; substrate adhesion-dependent cell spreading; vesicle-mediated transport; cell migration involved in heart development; positive regulation of extracellular matrix assembly; regulation of endocytic recycling; striated muscle tissue development
Cellular component: bicellular tight junction; cell junction; lateral plasma membrane; membrane; plasma membrane; sarcolemma; caveola; cell projection membrane
Genetic constraint (gnomAD): Loss-of-function variants: 24 observed, 36.87 expected, observed/expected ratio (o/e) 0.65, 90% interval 0.47 to 0.92. The upper end of that interval is the gene's LOEUF score, 0.92, which puts it in group 3 of 6, group 1 being the genes least tolerant of losing a copy. Missense variants: 408 observed, 443.54 expected, observed/expected ratio (o/e) 0.92, 90% interval 0.85 to 1. Synonymous variants: 157 observed, 153.31 expected, observed/expected ratio (o/e) 1.02, 90% interval 0.9 to 1.17.
Homologues: Orthologues: chimpanzee BVES (99% identical), macaque BVES (99% identical), dog POPDC1 (96% identical), rabbit POPDC1 (93% identical), guinea pig POPDC1 (92% identical), pig POPDC1 (91% identical), mouse Popdc1 (87% identical), rat Bves (84% identical), tropical clawed frog popdc1 (69% identical), zebrafish popdc1 (62% identical), Drosophila melanogaster bves (26% identical). Paralogues in human: POPDC2 (26% identical), POPDC3 (24% identical).
Diseases named in the same sentence as POPDC1 in open-access papers:
POPDC1 is named in the same sentence as 36 diseases in open-access papers, as found by Europe PMC text mining. Sharing a sentence is not in itself a finding about the gene and the disease. The quoted sentences say what the papers report.
cardiac arrhythmia (15 papers, 2014 to 2024). Any disturbances of the normal rhythmic beating of the heart or MYOCARDIAL CONTRACTION. "The functional conservation of cardiac arrhythmia phenotypes of POPDC1 mutations from zebrafish, mice, and humans suggests that the identified POPDC1 complexes are likely relevant in regulating cardiac function in the human heart as well." (PMID 36254885, 2022). "A homozygous missense variant in POPDC1 has been found in a family with cardiac arrhythmia and limb-girdle muscular dystrophy (LGMD)." (PMID 33261556, 2020). "Mutations in human POPDC1, POPDC2 and in human XIRP1, all cause pathological cardiac arrhythmias, suggesting a possible role for POPDC1/2 and XIRP1 interaction in normal cardiac conduction." (PMID 33261556, 2020). "Further support for the view that the FL/IDSPEW/F motif is directly involved in cyclic nucleotide binding is based on the identification of a POPDC1 p.S201F mutation, which has been identified in patients with muscular dystrophy and cardiac arrhythmia phenotypes." (PMID 31197601, 2019). "These might contribute to the observed ischaemia/reperfusion vulnerability of Popdc1-null mutant hearts, but may also be involved in causing the cardiac arrhythmia phenotypes in Popdc1 mutants." (PMID 24646234, 2014). "Mutations in blood vessel epicardial substance (BVES) also known as POPDC1 and POPDC2 have been associated with limb-girdle muscular dystrophy and cardiac arrhythmia." (PMID 36624536, 2023). "Consistent with its predominant expression in striated muscle, Popdc1 and Popdc2 null mutants in mouse and zebrafish develop cardiac arrhythmia and muscular dystrophy." (PMID 31197601, 2019). "The first mutation of POPDC1 discovered in patients is the recessive POPDC1S201F mutation, which was reported to be associated with cardiac arrhythmia and muscular dystrophy." (PMID 29534001, 2018). "Depletion of Popdc1 or Popdc2 in the mouse and zebrafish model systems also results in severe cardiac arrhythmias." (PMID 24646234, 2014). "Impaired calcium transients were also reported in cardiac myocytes isolated from Popdc1 null mutants, which may partially explain their cardiac arrhythmia phenotypes." (PMID 34940515, 2021). "These alterations might contribute to the observed ischaemia/reperfusion vulnerability of Popdc1-null mutant hearts, but may also explain in part the cardiac arrhythmia phenotypes in Popdc1 and -2 mutants." (PMID 27500161, 2014). "This interaction may be important as it is thought that POPDC1 has a modulatory effect on TREK-1, and dysregulation of this interaction may contribute to the cardiac arrhythmia phenotypes observed in POPDC knock-in (KI) and knockout (KO) mutants." (PMID 31197601, 2019).
limb-girdle muscular dystrophy (8 papers, 2016 to 2025). Limb-girdle muscular dystrophy (LGMD) is a heterogeneous group of muscular dystrophies characterized by proximal weakness affecting the pelvic and shoulder girdles. "Patients carrying mutations in POPDC1 develop a recessive form of limb-girdle muscular dystrophy (LGMDR25) with highly variable onset and in addition displaying sinus bradycardia and an AV-block of varying severity." (PMID 34940515, 2021). "Mutations in POPDC1, POPDC2 and POPDC3 have been recently identified in patients suffering from cardiac arrhythmia and/or limb-girdle muscular dystrophy, respectively." (PMID 34999055, 2022). "Although it is currently not known whether POPDC2 and POPDC3 also bind PDE4, mutation of leucine 155 to histidine in POPDC3, which corresponds to leucine 173 in POPDC1, was recently identified in a patient suffering from limb-girdle muscular dystrophy (LGMDR26, OMIM 605824)." (PMID 34999055, 2022). "Unlike the recessive syndrome associated with the other POPDC genes (i.e., POPDC1 and POPDC3-related limb-girdle muscular dystrophy), none of the affected individuals showed signs of muscular dystrophy." (PMID 40409267, 2025).
Sinus bradycardia (6 papers, 2016 to 2023). Bradycardia related to a mean resting sinus rate of less than 50 beats per minute. "The cardiac-specific knockout of Kcnk2, which encodes TREK-1, produces a stress-induced sinus bradycardia with a phenotypical manifestation that largely resembles the one described for Popdc1 and Popdc2 null mutants." (PMID 34940515, 2021). "Popdc1 and Popdc2 are highly expressed in the SAN and loss of function mutations in mice are causing a stress-induced sinus bradycardia phenotype 13." (PMID 34999055, 2022). "Therefore, it is possible, that the enhanced LTP and the stress-induced sinus bradycardia found in Popdc1 null mutant mice may be based on the same or related molecular defects." (PMID 34940515, 2021). "A cardiac specific knockout of Kcnk2, which encodes TREK-1, displays a stress-induced sinus bradycardia similar to the one observed in Popdc1 and Popdc2 null mutants, suggesting that the sinus bradycardia in POPDC mutants may in part be due to an impaired TREK-1 current." (PMID 28939104, 2017). "In contrast, Popdc1 and Popdc2 null mutants have a stress-induced sinus bradycardia, while an AV-block has not yet been described." (PMID 27347491, 2016).
AV block (4 papers, 2020 to 2025). "The mutations disrupting the regulation of TREK-1 by POPDC1 or POPDC2 proteins lead to the development of familial AV block." (PMID 34445768, 2021). "Furthermore, POPDC1 and POPDC2 double knockout animals exhibited signs of atrioventricular conduction disorder (AV block)." (PMID 34445768, 2021).
hepatocellular carcinoma (4 papers, 2017 to 2022). A malignant tumor that arises from hepatocytes. "Suppression of POPDC1 has further been shown to promote cell migration and invasion in hepatocellular carcinoma, and to promote tumorigenesis in colorectal cancer." (PMID 28954821, 2017). "This is consistent with suppression of POPDC1 protein and mRNA observed in various cancers including gastric cancer, colorectal cancer and hepatocellular carcinoma." (PMID 28954821, 2017). "Indeed, POPDC1 inhibits cell migration and invasion in hepatocellular carcinoma and colorectal cancer cells." (PMID 31817925, 2019). "This is also consistent with the hypothesis that POPDC1 is a tumor suppressor in colorectal cancer and hepatocellular carcinoma." (PMID 31817925, 2019). "Interestingly, the suppression of POPDC1 has been shown to promote cell migration and invasiveness of breast cancer cells, gastric cancer cells, and hepatocellular carcinoma cells." (PMID 31817925, 2019). "In human hepatocellular carcinoma (HCC), netrin-1, a laminin-related neuronal guidance molecule, negatively regulates POPDC1 expression through AKT activation." (PMID 34940515, 2021).
muscular dystrophy (4 papers, 2018 to 2025). Muscular dystrophy (MD) refers to a group of more than 30 genetic diseases characterized by progressive weakness and degeneration of the skeletal muscles that control movement. "We then conducted genetic burden analyses, wherein rare variants in POPDC2 are aggregated, with the phenotypes above and muscular dystrophy as this is a clinical hallmark of recessive syndromes associated with the two other members of the POPDC family (i.e., POPDC1 and POPDC3)." (PMID 40409267, 2025). "POPDC1’s negative control of the WNT signalling pathway may also provide novel mechanistic insight into the muscular dystrophy phenotypes present in carriers of POPDC1 mutations and in KO mutants in zebrafish and mice." (PMID 31197601, 2019). "Bi-allelic variants in POPDC1 and POPDC3 have been associated with muscular dystrophy, with and without CCD, respectively, while the affected individuals reported here presented with isolated cardiac disease." (PMID 40409267, 2025).
Bradycardia (3 papers, 2014 to 2022). A slower than normal heart rate (in adults, slower than 60 beats per minute). "Mutant mice with a deletion of either Popdc1 or Popdc2 exhibit severe stress‐induced bradycardia with high HR variability and long sinus pauses." (PMID 36254885, 2022). "Both POPDC1 and PDE4 are highly expressed in the SAN and Popdc1 and Popdc2 KO mice display a stress-induced sinus bradycardia." (PMID 34999055, 2022). "Interestingly, the cardiac phenotype, which is present in both, Popdc1 and Popdc2 null mutants, is characterized by a stress-induced sinus bradycardia, suggesting that Popdc proteins participate in cAMP signaling in the sinuatrial node." (PMID 27500161, 2014). "Given that deletion or mutation of POPDC1 often leads to loss of POPDC2 membrane localization, and deletion of either POPDC isoform closely phenocopies one another with respect to HR variability and stress‐induced bradycardia, POPDC1 likely heterodimerizes with POPDC2." (PMID 36254885, 2022). "Therefore it is likely that also the trafficking of other ion channels should depend on the interaction with Popdc proteins and defining these interactions might give a clue why Popdc1 and -2 mutants develop a stress-induced bradycardia phenotype." (PMID 27500161, 2014).
gastric cancer (3 papers, 2017 to 2021). A primary or metastatic malignant neoplasm involving the stomach. "Furthermore, suppression of POPDC1 has been correlated to enhanced metastasis and poor clinical outcomes in gastric cancer." (PMID 31817925, 2019). "POPDC1 and POPDC3 downregulation was described in several tumors, including colon and gastric cancers." (PMID 34069715, 2021). "Furthermore, POPDC1 expression is significantly suppressed at all clinical stages of breast and gastric cancer without correlation to clinical progression." (PMID 31817925, 2019).
heart failure (3 papers, 2013 to 2024). Inability of the heart to pump blood at an adequate rate to meet tissue metabolic requirements. "Previously, we reported the diminution of Popdc1 and its coding mRNA in end stage heart failure in humans that suggested a relationship between the evolution of myocardial dysfunction and the decrease in Popdc1." (PMID 24066022, 2013).
atrial fibrillation (2 papers, 2016 to 2017). A disorder characterized by an electrocardiographic finding of a supraventricular arrhythmia characterized by the replacement of consistent P waves by rapid oscillations or fibrillatory waves that vary in size, shape and timing and are accompanied by an irregular ventricular response. "Recently, POPDC1 was identified as a hub gene for atrial fibrillation (AF) using a weighted co-expression network analysis." (PMID 27347491, 2016).
breast carcinoma (2 papers, 2017 to 2019). "Secondly, we assessed the effects of loss and gain of POPDC1 functions on breast cancer cell migration and proliferation." (PMID 28954821, 2017). "Thirdly, cAMP interacts with and regulates POPDC1 expression in breast cancer cells and finally, cAMP-mediated inhibition of breast cancer cell migration and proliferation is potentially mediated via POPDC1 signalling." (PMID 28954821, 2017). "In conclusion, POPDC1 represents a druggable target that can potentially be manipulated to inhibit breast cancer cell migration and proliferation." (PMID 28954821, 2017). "We assessed the potential of POPDC1 as a novel target for inhibiting breast cancer cell migration and proliferation." (PMID 28954821, 2017). "Although the role of POPDC1 in breast cancer tumorigenesis remains to be established, POPDC1 presents a realistically druggable target for various reasons." (PMID 28954821, 2017). "Suppression of POPDC1 significantly promotes a malignant phenotype in breast cancer by promoting cell migration in MCF7, MDA231 and SKBR3 cells, and cell proliferation in the more aggressive MDA231 and SKBR3 cells." (PMID 28954821, 2017). "Given that overexpression of POPDC1 has been shown to attenuate colorectal cancer tumour growth and metastasis in mice, we next asked if POPDC1 overexpression affects breast cancer cell migration and proliferation." (PMID 28954821, 2017). "To assess the effects of cAMP on POPDC1 expression in breast cancer cells, we next asked if up-regulation of cAMP with the cAMP analogue Sp-8-Br-cAMPS can affect the levels of POPDC1." (PMID 28954821, 2017). "Secondly, suppression of POPDC1 promotes cell migration and proliferation in breast cancer cells, which are significantly inhibited by the overexpression of POPDC1." (PMID 28954821, 2017). "This dataset confirms that cAMP indeed interacts with POPDC1 and can increase its presence and stability in breast cancer cells." (PMID 28954821, 2017). "To confirm if cAMP interacts with POPDC1 in breast cancer cells, we performed a pull-down assay with cAMP agarose beads." (PMID 28954821, 2017). "Consistent with this hypothesis, cAMP upregulates the expression of POPDC1 in breast cancer cells, which likely leads to an inhibition of cell migration and proliferation." (PMID 31817925, 2019). "However, cAMP-mediated inhibition of breast cancer cell adhesion, migration and proliferation are consistent with the effects seen after forced expression of POPDC1 in breast cancer cells." (PMID 31817925, 2019). "However, mechanisms by which POPDC1 regulates cell migration and proliferation in breast cancer need to be clearly elucidated in order to permit development of directed therapeutics to take advantage of POPDC1 and its diverse molecular role." (PMID 28954821, 2017). "We have further demonstrated the functional relevance of POPDC1 dysregulation in breast cancer." (PMID 28954821, 2017). "We hypothesize that dysregulation of POPDC1 promotes malignant phenotypes in breast cancer and that restoration of POPDC1 can potentially inhibit cell migration and proliferation, and revert cells to a less malignant phenotype." (PMID 28954821, 2017). "Furthermore, suppression of POPDC1 significantly promoted cell proliferation in the more aggressive breast cancer cell lines MDA231 and SKBR3." (PMID 28954821, 2017). "It is therefore essential to determine whether cAMP-mediated suppression of breast cancer cell migration and proliferation is indeed dependent on cAMP-induced increase in POPDC1 protein levels." (PMID 28954821, 2017). "Expression and cell membrane localization of POPDC1 is reduced in breast cancer cells." (PMID 28954821, 2017). "POPDC1 was significantly suppressed with reduced cell membrane localization in breast cancer cells." (PMID 28954821, 2017). "To test this hypothesis, we firstly determined the expression levels of POPDC1 in breast cancer cells in comparison with normal breast cells." (PMID 28954821, 2017).